VCAM1 (vascular cell adhesion molecule 1)
Diseases named in the same sentence as VCAM1 in open-access papers (continued):
Sharing a sentence is not in itself a finding about the gene and the disease.
Hydrocephalus (1 paper, 2025). Hydrocephalus is an active distension of the ventricular system of the brain resulting from inadequate passage of CSF from its point of production within the cerebral ventricles to its point of absorption into the systemic circulation. "We identified significant increases in vascular injury proteins (CRP, SAA, ICAM-1, and VCAM-1) at 5 days post-injury in the serum and CSF when compared to healthy, age-matched and unaffected (hydrocephalus) controls, respectively." (PMID 40427506, 2025). "aSAH patients demonstrated significantly higher levels of VCAM-1, ICAM-1, and SAA in the CSF for both timepoints when compared with hydrocephalus patient controls." (PMID 40427506, 2025).
Hypercalcemia (1 paper, 2022). An abnormally increased calcium concentration in the blood. "The coexistence of extrapulmonary disease was associated with elevated circulating vascular cell adhesion molecule 1, while cases with hypercalcemia had higher thrombomodulin concentration." (PMID 36494464, 2022).
hyperreactivity (1 paper, 2023). "IL-13 causes goblet cell metaplasia, bronchial hyperreactivity, and eosinophil extravasation by stimulating the expression of intercellular adhesion molecule 1 (ICAM-1) and vascular cell adhesion molecule 1 (VCAM-1)." (PMID 37569846, 2023).
hypertriglyceridemia (1 paper, 2019). A laboratory test result indicating elevated triglyceride concentration in the blood. "The previous report showed the levels of soluble E-selectin, soluble ICAM-1, and soluble VCAM-1 in the serum of patients with hypertriglyceridemia were increased, and multivariable analyses revealed that this increase was independent of other risk factors." (PMID 31550292, 2019).
hypertrophic cardiomyopathy (1 paper, 2026). A condition in which the myocardium is hypertrophied without an obvious cause. "ICAM-1 and VCAM-1 are upregulated in EC after Gb3 stimulation, and VEGF has been associated with hypertrophic cardiomyopathy in FD patients." (PMID 41545379, 2026).
Hypervolemia (1 paper, 2010). An increase in the amount of intravascular fluid, particularly in the volume of the circulating blood. "Furthermore, hypervolemia was associated with alveolar and endothelium damage as well as increased IL-6, VCAM-1 and ICAM-1 mRNA expressions in lung tissue; 2) RMs reduced alveolar collapse regardless of volemic status." (PMID 20546573, 2010). "Furthermore, hypervolemia was associated with alveolar and endothelium damage as well as increased mRNA expression of IL-6, VCAM-1 and ICAM-1 in lung tissue." (PMID 20546573, 2010). "We observed that: 1) hypervolemia increased lung W/D ratio with impairment of oxygenation and Est,L, and was associated with alveolar and endothelial cell damage and increased IL-6, VCAM-1, and ICAM-1 mRNA expressions; and 2) RM reduced alveolar collapse independent of volemic status." (PMID 20546573, 2010).
hypotension (1 paper, 2018). "The gestational hypotension could be associated with preterm delivery, and we found that serum level of VCAM-1 is one of the factors in differentiating FPD and PD." (PMID 29850638, 2018).
hypothyroidism (1 paper, 2016). Abnormally low levels of thyroid hormone. "The results showed that in vivo, the expression of osteopontin (OPN) vascular cell adhesion molecule (VCAM-1), and levels of integrin αvβ3 in the aortic tissue in SCH and Hypothyroidism (CH) groups was higher than in the control group." (PMID 27657042, 2016). "In conclusion, rats with subclinical hypothyroidism showed high levels of OPN, integrin αvβ3, and VCAM-1 expression in their aortic tissues." (PMID 27657042, 2016).
hypoxia (1 paper, 2025). A decrease in the amount of oxygen in the body. "Although a recent manuscript reported that inhibition of VCAM1 activation protects against BBB breakdown in a mouse model of chronic cerebral hypoxia, in our experiments VCAM-1 blockade alone did not reduce albumin extravasation." (PMID 40259346, 2025).
inflammatory skin disease (1 paper, 2022). Inflammatory skin disorders covers a broad category that includes many conditions ranging in severity, from mild itching to grave medical health complications These disorders are common in people of all ages and races. "Additionally, griseofulvin has been shown effective for inflammatory skin diseases through inducing inhibitory effects on vascular cell adhesion molecule 1 (VCAM-1) in both TNF-alpha and IL-1 stimulated human dermal microvascular endothelial cells (HDMEC)." (PMID 36296627, 2022).
intrahepatic cholangiocarcinoma (1 paper, 2025). A carcinoma that arises from the intrahepatic bile duct epithelium in any site of the intrahepatic biliary tree. "It was reported that circRNA MALAT1 promoted the progression of intrahepatic cholangiocarcinoma by competing with miR-512-5p to bind to VCAM1, leading to upregulation of VCAM1 transcription and activation of PI3K/AKT signaling pathway." (PMID 40584619, 2025).
intrahepatic cholestasis (1 paper, 2022). A cholestasis characterized by impairment of the bile flow caused by obstruction located in the liver. "The expression of vascular cell adhesion molecule 1 (VCAM-1), the target of miR-590-3p, is reduced in intrahepatic cholestasis in pregnancy." (PMID 35563893, 2022).
Kawasaki disease (1 paper, 2019). A rare inflammatory disease characterized by an acute febrile, systemic, self-limiting, medium-vessel vasculitis primarily affecting children. "Mice with Kawasaki’s disease, an inflammatory disease model, present impaired endothelium-dependent vasodilation accompanied by increased caspase-1, IL-1β, and VCAM-1 expression." (PMID 32009974, 2019).
kidney cancer (1 paper, 2023). Primary or metastatic malignant neoplasm involving the kidney. "Moreover, the VCAM1 protein expression between normal samples and kidney cancer samples was further validated using The Human Protein Atlas." (PMID 37622107, 2023).
Krebs 2 carcinoma (1 paper, 2022). "The obtained data confirmed the strong overexpression of Mreg, Prg4, Col3a1, Selp, Marco, and Fgfr1 genes in Krebs-2 carcinoma, as well as Cdh11, Col4a5, Vcam1, Megf6, Scarf2, Scart1, and Cd14 genes in HH47." (PMID 36555446, 2022).
lentivirus infection (1 paper, 2022). Virus diseases caused by the Lentivirus genus. "We knockdown the expression of ANRIL in endothelial cells under IS stimulation, and the results showed that compared with scramble, ANRIL shRNA lentivirus infection (Sh-ANRIL) lead to eNOS expression upregulated, while the expression of VCAM-1 and vWF decreased." (PMID 35906216, 2022).
leprosy (1 paper, 2016). Leprosy is a chronic infectious disease affecting primarily the skin and peripheral nervous system. "We observed significant increase of VCAM-1 circulating levels innon-reactional leprosy (p = 0.0009)." (PMID 27706378, 2016). "ELISA evaluation of VCAM-1 in NR leprosy (62.5 ± 14.7) demonstrated higher levels thanHC (40.9 ± 8.9) (p = 0.0009)." (PMID 27706378, 2016). "We suggest a comparable role of VCAM-1 with the formeradhesion molecules, in the endothelium of leprosy patients." (PMID 27706378, 2016). "This studyaimed to investigate the endothelial factors VCAM-1, VEGF, TM and TF in serum samples andskin lesions of leprosy patients." (PMID 27706378, 2016). "The present study evaluated the expression ofendothelial factors in skin lesions and serum samples of leprosy patients.Immunohistochemical analysis of skin samples and serum measurements of VCAM-1, VEGF,tissue factor and thrombomodulin were performed in 77 leprosy patients and 12controls." (PMID 27706378, 2016). "We could not reject the possible influence of clinicalforms of leprosy in final results of VCAM-1." (PMID 27706378, 2016).
lichen planus (1 paper, 2013). A chronic, recurrent, pruritic inflammatory disorder of unknown etiology that affects the skin and mucus membranes. "Thirty cases of oral normal mucosa associated with lichen planus showed that the VCAM1 has increased significantly in comparison to normal mucosa (p<0.001)." (PMID 24551788, 2013). "VCAM1 expression has been significantly more in lichen planus than normal mucosa (p<0.001)." (PMID 24551788, 2013). "In the present study, VCAM1 and ICAM1 expression was significantly higher in lichen planus in comparison to normal mucosa." (PMID 24551788, 2013). "Regarding the fact that VCAM1 and ICAM1 are expressed by endothelial cells and leukocytes, the increase of their expression can be attributed to the increase in blood vessels and leukocytes in lichen planus." (PMID 24551788, 2013). "No case of higher or equal VCAM1 expression was observed in normal mucosa compared to lichen planus." (PMID 24551788, 2013).
minimal-change disease (1 paper, 2012). "In contrast, patients with minimal-change disease had low levels of VCAM-1, comparable with those found in the healthy controls." (PMID 22788914, 2012).
monocytic leukemia (1 paper, 2017). "Notably, recombinant SlaA induced ICAM1 and VCAM1 expression in human umbilical vein endothelial cells (HUVECs), resulting in enhanced adhesion of human monocytic leukemia (THP-1) cells." (PMID 28713783, 2017).
myositis (1 paper, 2025). "The hPBMC mice exhibit elevated serum levels of creatine kinase and aspartate transaminase, markers of myositis, and increased expression levels of myositis-related genes, such as vascular cell adhesion molecule 1, intercellular adhesion molecule 1, and serum amyloid A1, in muscle tissues." (PMID 39810259, 2025).
non-Hodgkin lymphoma (1 paper, 2022). Distinct from Hodgkin lymphoma both morphologically and biologically, non-Hodgkin lymphoma (NHL) is characterized by the absence of Reed-Sternberg cells, can occur at any age, and usually presents as a localized or generalized lymphadenopathy associated with fever and weight loss. "Finally, VCAM1 upregulation is associated with a poor prognosis for patients with non-Hodgkin's lymphomas, and VCAM1 is under investigation as a potential serum biomarker for assessing disease progression." (PMID 36873459, 2022).
obstructive sleep apnea (1 paper, 2023). "The present study, based on our information, is the first to investigate the relationship between serum biomarkers VCAM-1 and ICAM-1, EFT, and the CVR predicted by SCORE-2 and SCORE-2OP risk tools in patients with obstructive sleep apnea." (PMID 38255155, 2023).
oncocytoma (1 paper, 2017). "For example, vascular cell adhesion molecule 1 (VCAM1) was reportedly significantly up-regulated in ccRCC and pRCC, whereas it was down-regulated in chRCC and oncocytoma." (PMID 29208006, 2017).
Onset (1 paper, 2022). The age group in which disease manifestations appear. "In a study from our centre of adolescent participants with early-onset psychosis, reduced levels of PSEL and VCAM-1 and no significant alterations of ICAM-1, MadCAM-1, JAMA or NCAD, were found." (PMID 35856063, 2022).
open-angle glaucoma (1 paper, 2022). Chronic outflow obstruction of the eye's drainage canals that can lead to increased internal eye pressure and optic nerve damage. "Moreover, most recently, 127 loci associated with open-angle glaucoma have been identified, with specific genes, such as RERE, VCAM1, ZNF638, SMAD6 potentially conferring open-angle glaucoma risk." (PMID 38983528, 2022).
oral lichen planus (1 paper, 2013). Oral lichen planus is a chronic inflammatory oral condition of unknown aetiology characterized by T-cell-mediated chronic immune response and abnormal epithelial keratinization cycle. "Mann-Whitney test was used to compare the percentage of stained cells in oral lichen planus and normal mucosa, and the results showed significant increase in VCAM1 and ICAM1 expression in oral lichen planus compared to normal mucosa (p<0.001 and p<0.001)." (PMID 24551788, 2013). "Regarding the results, it seems that high expression of VCAM1 and ICAM1 is related to oral lichen planus." (PMID 24551788, 2013). "In conclusion, higher expression of VCAM1 and ICAM1 were seen in oral lichen planus compared to normal oral mucosa which appears to be involved in pathogenesis of oral lichen planus." (PMID 24551788, 2013). "The aim of this study is the immunohistochemical evaluation of VCAM1 and ICAM1 in oral lichen planus and to compare these two markers with normal mucosa for evaluation of angiogenesis." (PMID 24551788, 2013). "VCAM1 and ICAM1 expression significantly increased compared to normal mucosa in oral lichen planus according to the percentage of stained cells (p=0.000& p=0.000, Mann-Whitney test)." (PMID 24551788, 2013).
overactive bladder (1 paper, 2025). Symptom of overactive detrusor muscle of the urinary bladder that contracts with abnormally high frequency and urgency. "In addition, a proteomic study in women with overactive bladder (OAB) identified vascular cell adhesion molecule-1 (VCAM-1) as the only urinary protein significantly different from controls, suggesting a possible role as a diagnostic biomarker that warrants validation in larger cohorts." (PMID 41226837, 2025).
pancreatic disease (1 paper, 2012). "VCAM-1 mediates the adhesion of eosinophils, lymphocytes, monocytes, and basophils to vascular endothelium and has been shown to be upregulated in pancreatic disease; however, its role in mixed IPMN and cancer remains unclear." (PMID 23326260, 2012).
peripheral vascular disease (1 paper, 2015). Any disorder affecting blood flow through the veins or arteries outside of the heart. "The fact that soluble VCAM-1, but not ICAM-1, remained the only predictor of c-IMT in hypertensive patients with peripheral vascular disease supports this hypothesis." (PMID 26066045, 2015).
polycythemia (1 paper, 2024). Abnormally high mass or concentration of red blood cells in the blood, either due to an increase in erythropoiesis or a decrease in plasma volume. "TFPI mAb treatment similarly decreased PB RBC numbers and Hb, and reduced F4/80+CD169+Vcam-1+ macrophage heme content in hypoxia-induced polycythemia mice." (PMID 38729948, 2024).
polyp (1 paper, 2014). A usually exophytic mass attached to the underlying tissue by a broad base or a thin stalk. "Nasal polyp tissues showed higher gene expression levels of the adhesion molecules P-selectin (1.62-fold, n = 7), PSGL1 (1.74-fold, n = 7), and VCAM1 (2.16-fold, n = 7) compared to associated inferior turbinates." (PMID 24995349, 2014).
posterior uveitis (1 paper, 2021). Inflammation of the choroid as well as the retina and vitreous body. "High expression levels of these adhesion molecules have been reported in posterior uveitis in humans and in murine EAU with VCAM1 expression in the perivascular extensions of RMG in uveitic murine eyes." (PMID 33806940, 2021).
Priapism (1 paper, 2018). A painful and harmful medical condition in which the erect penis doesn't return to its flaccid state, despite the absence of both physical and psychological stimulation, within four hours. "We have previously reported a continuous rise in ICAM-1, VCAM-1, and E-selectin in HbSS patients with sub-phenotypes including priapism and leg ulcers at a tertiary hospital." (PMID 30577523, 2018).
proliferative diabetic retinopathy (1 paper, 2020). Advanced retinopathy due to diabetes mellitus characterized by the formation of new vessels in the retina. "In particular, increased expression of cell adhesion molecules such as VCAM1, ICAM1, and ICAM2 is a feature of proliferative diabetic retinopathy (PDR), where they increase recruitment of leukocytes to the endothelium and disrupt blood flow, a process termed leukostasis." (PMID 32811565, 2020).
pterygium (1 paper, 2021). A wedge-shaped fibrovascular lesion arising from the bulbar conjunctiva and extending to the cornea. "VCAM-1 is a member of the immunoglobulin superfamily and an important cell adhesion molecule, the positive rate of which in pterygium is higher than that observed in conjunctiva." (PMID 33790949, 2021). "Furthermore, through protein-protein interaction network and mRNA-lncRNA co-expression network analysis, key mRNAs including FN1, VCAM1, and MMP2, and key lncRNAs including MIR4435-2HG and LINC00968 were screened and might be involved in the pathogenesis of pterygium." (PMID 33790949, 2021).
pulmonary edema (1 paper, 2023). Accumulation of fluid in the lung tissues causing disturbance of the gas exchange that may lead to respiratory failure. "Prevotella and Butyrivibrio can produce various SCFAs, which can enter the brain through the blood–brain barrier, downregulate ICAM-1 and VCAM-1 levels, and reduce brain and pulmonary edema." (PMID 38004668, 2023).
pulmonary TB (1 paper, 2021). "When only the individuals with pulmonary TB were compared to those with ORD, significant differences were observed for SAA, CRP, VEGFR3, RANTES, Pentraxin3, Ferritin, CCL18, MPO, GDF-15, MMP-1, PDGF-BB, Procalcitonin, MDC, Myoglobin, and VCAM-1." (PMID 33732236, 2021).
pulpitis (1 paper, 2022). Inflammation of the dental pulp. "In conclusion, in this study, we revealed miR‐126 and VCAM‐1 variations in patients with irreversible pulpitis." (PMID 35334501, 2022). "In this study, we investigated the miR‐126 and VCAM‐1 variation in inflamed pulp tissues and determined the inhibitory function of miR‐126 in VCAM‐1 and pulpitis using human dental pulp cells (DPCs)." (PMID 35334501, 2022). "We investigated variations of miR‐126 and VCAM‐1 in inflamed patient pulp tissues and determined potential roles of miR‐126 in pulpitis using human dental pulp cells (hDPCs) in vitro." (PMID 35334501, 2022). "The overexpression of miR‐126 delivered by PEI effectively downregulated VCAM‐1 and the IL‐1β, a key pro‐inflammatory cytokine in pulpitis, under LPS challenge in vitro." (PMID 35334501, 2022). "The irreversible pulpitis significantly reduced miR‐126 and increased the transcript of VCAM‐1 in pulp tissues (p < 0.05)." (PMID 35334501, 2022). "Like other pro‐inflammatory cytokines, VCAM‐1 has been demonstrated to play critical roles in inflammation in pulpitis by regulating inflammatory cell migration and binding on the endothelium surface." (PMID 35334501, 2022). "miR‐126 is involved in pulpitis and downregulated the VCAM‐1 and IL‐1β in DPCs." (PMID 35334501, 2022). "Vascular cell adhesion molecule (VCAM‐1) mediates pulpitis via regulating interleukin (IL)‐1β." (PMID 35334501, 2022). "VCAM‐1 was reported to actively involve the inflammation of pulpitis in tooth preparation." (PMID 35334501, 2022). "These evidence indicate that VCAM‐1 may contribute to the excessive inflammation in pulpitis, and thus, the modulation of VCAM‐1 may effectively attenuate the inflammatory reaction of pulpitis." (PMID 35334501, 2022). "Because miR‐126 directly targets VCAM‐1, the reduced miR‐126 by LPS may contribute at least partially to the upregulation of VCAM‐1 in pulpitis and DPCs in vitro." (PMID 35334501, 2022). "In addition, we confirmed the function of miR‐126 overexpression in reducing VCAM‐1 and interleukin 1 beta (IL‐1β), a pro‐inflammatory cytokine participating in pulpitis, in human DPCs under the stimulation of LPS." (PMID 35334501, 2022). "LPS effectively downregulated miR‐126 that might contribute to the pulpitis's inflammatory progression by activating VCAM‐1 and IL‐1β." (PMID 35334501, 2022).
respiratory syncytial virus infection (1 paper, 2013). "Increased adhesion molecules expression, such as ICAM-1 and VCAM-1, on A549 lung epithelial cells was reported upon respiratory syncytial virus infection." (PMID 24073006, 2013).
retinoblastoma (1 paper, 2023). A malignant tumor that originates in the nuclear layer of the retina. "Retinoblastoma cell derived‐exosomes induce VCAM1 expression in endothelial cells to promote angiogenesis." (PMID 36965158, 2023).